MMP2 (matrix metallopeptidase 2)
Diseases named in the same sentence as MMP2 in open-access papers (continued):
Sharing a sentence is not in itself a finding about the gene and the disease.
COVID-19 (continued). "Studies utilizing cultured endothelial cells treated with COVID-19 patient plasma in vitro showed similar changes in HA, as well as hyaluronidase, MMP2, MMP9, and cathepsin activity." (PMID 35872762, 2022). "As such, the plasmatic levels of MMP2 and MMP9 in patients with severe COVID-19 documented a significant association between their levels and disease severity with the potential to predict the risk of in-hospital death." (PMID 35893698, 2022). "After comparing the collected genes, 460 host factors common to COVID-19 and dengue were found, including MMP2, PDF, PFKP, SLC25A3, IGF1, CCL4, TLR4, and AhR, and further analysis of interaction networks was performed." (PMID 34394108, 2021). "The role of the plasma levels of MMP2 has been reported in hypertensive COVID-19 patients." (PMID 39965032, 2025). "MMP-2 has shown a correlation with mortality in patients with COVID-19, so it could be a potential prognostic predictor for patients with COVID-19." (PMID 38338840, 2024). "Along with neutrophil infiltration and its byproducts, such as reactive oxygen species (ROS), the overexpression of the MMP-2/MMP-8 axis also boosted lipid peroxidation, which may facilitate the severe loss of lung tissue in COVID-19." (PMID 39727640, 2024). "The authors hypothesized that increased levels of mRNA MMP-2 in hypertensive patients with COVID-19 may result from an overactivated RAS." (PMID 37372128, 2023). "Furthermore, MMP-9 levels increased while MMP-2 levels decreased in COVID-19 patients, which is consistent with HCoV-OC43 infection in MRC-5 cells." (PMID 37447286, 2023). "The gene MMP2 has been recognized as a hub gene in COVID-19-infected patients." (PMID 36913345, 2023). "Previous COVID-19 findings showed elevated MMP-2 and MMP-9 levels in hospitalized patients." (PMID 36831321, 2023). "Interestingly, MMP-2 level was decreased in the plasma of patients with COVID-19 compared with that of the control group." (PMID 36142454, 2022). "We emphasized a relative looping in our data when ROS formation by oxidative stress, probably due to neutrophils activity, could trigger MMP-2 activation and MMP-2 function could increase ROS formation in the lung of COVID-19 patients." (PMID 35625532, 2022). "Furthermore, higher MMP-2 and MMP-9 levels were independent risk factors for mortality in COVID-19 patients." (PMID 36079011, 2022). "Besides MMP-9, which has been shown to be associated with a high risk of mortality, others, such as MMP-1, MMP-2, MMP-8, and MMP-13 have also been correlated with disease severity and increased risk of death, especially during the acute phase of COVID-19." (PMID 37372128, 2023). "Moreover, MMP-2 levels were positive and significantly correlated with lipid peroxidation concentration, suggesting another positive looping of neutrophils producing ROS species; ROS triggers MMP-2 activation and MMP-2 enhanced oxidative stress in the COVID-19 lung." (PMID 35625532, 2022). "However, only the active form of MMP-2 was extremely associated with non-survival COVID-19 patients." (PMID 35625532, 2022). "Herein, we investigated the plasma levels of MMP-9, TIMP-1 as well as the plasma activity of MMP-2 and MMP-9 in a cohort of well-characterized patients with COVID-19 at an acute stage of the disease and after three months from hospital discharge." (PMID 37509076, 2023). "Based on the ratio data of the present research, we extend to MMP-2 and NFL as markers of COVID-19 morbidity and mortality as also shown by the AUC data of the ROC curves." (PMID 36831321, 2023). "We observed increased levels of plasma MMP-2 and comparable levels of plasma MMP-9 in COVID-19 with pneumonia compared to healthy controls." (PMID 36835000, 2023). "By contrast, a previous study has indicated a decrease in plasma MMP-2 and an increase in plasma MMP-9 in COVID-19." (PMID 36835000, 2023).
COVID-19 (continued). "Alongside the significant elevation of MMP-1 observed in COVID-19 patients, there have been reports indicating that the SARS-CoV-2 spike protein can stimulate the expression of MMP-2 to a lesser extent, as well as MMP-3." (PMID 37372128, 2023). "We observed that TAF samples from COVID-19 and non-COVID-19 individuals expressed high levels of pro-MMP-9 and pro-MMP-2 by zymogram." (PMID 35625532, 2022). "Metalloproteases have a longstanding link to the progression of respiratory damage, and MMP-2, MMP-3, MMP-7, and MMP-9 have all been shown to correlate with COVID-19 severity." (PMID 36298651, 2022). "In a study conducted on 53 patients with a severe COVID-19 course, increased MMP-9 values and decreased MMP-2 values in their plasma were observed compared to the control group." (PMID 36551272, 2022). "Genes whose expressions were altered in endothelial cells under the influence of COVID-19 included TIMP1, MMP2, MMP11, VWF, ICAM1, and ICAM2, which affect coagulation and the development of inflammation." (PMID 36551272, 2022). "Taken together, our data demonstrated that both sHLA-G and sTREM-1 levels on TAF samples were elevated in COVID-19 patients and sTREM-1 positively correlated with MMP-8, while sHLA-G levels positively correlated with both MMP-2 and MMP-8 expression." (PMID 35625532, 2022). "Several enzymes can be used as a target for COVID-19 therapeutics including PI3K ̧ mTOR, growth factor receptor, RAF, MAP2K2, FLT3, AXL, AKT, and matrix metalloprotease MMP2 and MMP9." (PMID 35251015, 2022). "The primary aim of this study was to explore CSF and plasma NfL levels as well as CSF MMP-2 and MMP-9 levels in COVID-19 patients with severe neurological symptoms." (PMID 36010557, 2022). "This prospective longitudinal study investigates the sustained dysregulation of matrix metalloproteinases (MMP)-2 and MMP-9 and its relationship with evolving systemic inflammation and endothelial dysfunction in convalescent COVID-19 patients, with comparative analysis to IPF." (PMID 41598609, 2026). "In the lungs of patients with non-survival COVID-19, MMP-2 and MMP-8 expression were elevated and correlated with the release of sTREM-1 and sHLA-G." (PMID 39727640, 2024). "MMP-2 and MMP-9 are downregulated in severe COVID-19 patients." (PMID 38338840, 2024). "We also predicted that the ratios of BDNF and NFL with MMP-2 and MMP-9 could be considered early predictors of COVID-19 mortality." (PMID 36831321, 2023). "It is worth noting here a recent finding that observed higher levels of plasma and CSF NfL and MMP-2 in the acute phase of COVID-19 with ARDS compared to non-ARDS." (PMID 37243203, 2023). "Indeed, pro-MMP-2 and pro-MMP-9 were present in all TAF samples from non-COVID-19 and COVID-19 patients." (PMID 35625532, 2022). "MMP-2 and MMP-8 were unambiguously elevated proteinases in the lung of patients with COVID-19." (PMID 35625532, 2022). "Although we observed high diversity of MMPs in lung tissue from COVID-19 patients by proteomics, we specified the expression and enzyme activity of MMP-2 in tracheal-aspirate fluid (TAF) samples from intubated COVID-19 and non-COVID-19 patients." (PMID 35625532, 2022). "Indeed, epithelial cells from bronchoalveolar lavage fluid (BALF) on severe COVID-19 showed elevated frequencies of MMP-7+ and MMP-9+ and a tendency to increase portions of MMP-2+ and MMP-13+ compared to mild cases." (PMID 35625532, 2022). "MMP-2, MMP-7, MMP-8, and MT1-MMP were increased in the lungs of patients with COVID-19." (PMID 36142454, 2022). "Since we had evidence of increased expression of MMP-14 and MMP-7 in COVID-19 lung tissue by proteomics reanalysis, both described activation pathways that could be effective in TAF samples to produce active-MMP-2 and active-MMP-8." (PMID 35625532, 2022). "Indeed, the TAF samples of COVID-19 patients presented a high amount of MMP-8, such as high levels of MMP-2." (PMID 35625532, 2022).
COVID-19 (continued). "Additionally, in neuro-COVID-19 patients, increased levels of both plasma and CSF NfL and MMP-2 (a form of MMPs) were found in ARDS compared to non-ARDS groups." (PMID 37243203, 2023). "Together, overexpression of the MMP-2/MMP-8 axis, in addition to neutrophil infiltration and products, such as reactive oxygen species (ROS), increased lipid peroxidation that could promote intensive destruction of lung tissue in severe COVID-19." (PMID 35625532, 2022). "Furthermore, comparing non-survival with survival COVID-19 patients, we observed a significant increase in MMP-2 and MMP-8 levels in the non-survival group, compared to the survival group and the non-COVID-19 group." (PMID 35625532, 2022). "Using meta-analysis, we demonstrated that the MMP2 pooled SMD in 5 distinct GEO datasets was 0.54, 95% CI (0.13.0.96), and ultimately, meta-analysis revealed that the COL3A1 pooled SMD of late stages of COVID-19 was 0.84, 95% CI (0.24,1.44) when compared to controls." (PMID 36248845, 2022). "Another report showed that the plasma MMP-2 levels decreased while MMP-9 levels increased in severe COVID-19 patients, but the COVID-19 non-survivors had higher MMP-2 levels than COVID-19 survivors, which is considered to be related to the activation of the renin–angiotensin system." (PMID 35741101, 2022). "We therefore measured the activities of matrix metalloproteinases (MMP2/9) and cathepsin D — proteases with known roles in endothelial injury — and found that MMP and cathepsin D activities are significantly increased in patients with COVID-19 compared with healthy donors." (PMID 34314391, 2021). "Of relevance to the current context, a recent study demonstrated that plasma levels of MMP-2 were increased in hypertensive patients with COVID-19 compared to normotensive patients, although lower than those observed in non-hypertensive patients affected by COVID-19." (PMID 37372128, 2023). "Although considered plasma prognostic biomarkers, the MMP-2 and MMP-8 pathways in the lung could become the target of specific therapies, including those proposed to diminish cell infiltration, viral immunosuppression response, oxidative stress, and tissue damage during COVID-19." (PMID 35625532, 2022). "As for the modifications we found in MMP-2 and the absence of alterations in MMP-9, it is well known that COVID-19 predominantly affected the respiratory tract leading to acute lung failure as the most severe outcome." (PMID 36831321, 2023). "We found significant differences due to COVID-19 disease severity for both BDNF and NFL but not for NGF in the ratios with MMP-2 or MMP-9." (PMID 36831321, 2023). "Considering the total protein form by ELISA, MMP-2 and MMP-8 were significantly higher in TAF from patients with COVID-19 compared to non-COVID-19." (PMID 35625532, 2022). "This target proteomics approach indicated that MMP-2, MMP-7, MMP-8, and MMP-14 figured out the COVID-19 perturbation with a significant increase compared to non-COVID-19 individuals." (PMID 35625532, 2022). "It appears partly reasonable with our results from proteomics reanalysis, which showed a significant increase in detection of MMP-2, MMP-7, MMP-8, and MMP-14, but not the expression of the MMP-9 protein, in lung tissue from COVID-19 compared to non-COVID-19 subjects." (PMID 35625532, 2022). "COL3A1 expression was increased in COVID-19 compared to controls, and although all GSE statistics of MMP2-positive cells were not significant, MMP2-positive cells were statistically differentially upregulated in late stage of EndMT by meta-analysis of GSE data." (PMID 36248845, 2022). "Additionally, plasma hyaluronidase activity was higher in the ICU COVID-19 patients vs. the non-ICU patients, and plasma MMP2, MMP9 and cathepsin D activities (enzymes which may cleave GAG-anchoring proteins) were significantly increased in COVID-19 patients vs. healthy controls." (PMID 35872762, 2022).
cardiac hypertrophy (41 papers, 2010 to 2025). "Prominent phenotypic features of the full length MMP-2 cardiac transgenic mice were progressive cardiomyocyte and ventricular hypertrophy associated with systolic dysfunction." (PMID 23874529, 2013). "Our study demonstrated that chronic administration of Ang II significantly increased the expression of cardiac chymase, chymase-containing mast cells, TGF-β1, and MMP-2, all of which are associated with the development of cardiac hypertrophy, fibrosis, and diastolic dysfunction." (PMID 40943161, 2025). "Human and neonatal rat cardiomyocytes treated with recombinant leptin were more susceptible to progression of cardiac hypertrophy, as indicated by increased cell size, elevated matrix metalloproteinase-2 (MMP-2) activity, and endothelin-1-induced rise in ROS levels." (PMID 32655492, 2020). "Furthermore, by searching the database, we can easily find that, in the pressure overload model of heart disease, MMP2-deficient mice showed reduced myocardial hypertrophy and fibrosis while MMP9 deficiency partially improved myocardial hypertrophy and fibrosis following pressure overload." (PMID 32982761, 2020). "Similar trends were also observed in other markers of pathological cardiac hypertrophy such as Ctgf (connective tissue growth factor), Mmp2 (matrix metalloproteinase‐2) and Acta2 (α‐smooth muscle actin; P=0.080 by Šídák's post hoc test)." (PMID 39921516, 2025). "Ang II treatment led to elevated cardiac expression of chymase, TGF-β1, and MMP-2, and increased the number of chymase-positive mast cells, resulting in notable cardiac hypertrophy and fibrosis." (PMID 40943161, 2025). "In our previous study, we found that increased SIRT3 expression in the myocardium of a porcine model of pathological myocardial hypertrophy effectively inhibited the expression of MMP2 and MMP9, limiting the progression of pathological myocardial hypertrophy." (PMID 40893347, 2025). "Under angiotensin II (AngII) infusion in MMP-2 knockout mice, cardiac hypertrophy progressed earlier and with greater severity, thereby indicating a protective role of MMP-2 in progression of cardiac hypertrophy." (PMID 33400052, 2021). "It has been demonstrated that captopril improved ventricular hypertrophy in rats by suppressing MMP-2 and MMP-9 expression." (PMID 30347737, 2018). "More important, MMP-2 has been shown to mediate β-AR-induced apoptosis in ventricular myocytes and cardiac hypertrophy in rats." (PMID 28855859, 2017). "Both echocardiographic and MMP-2 results all indicated a cardiac hypertrophy after being operated for 28 days, while QSYQ can improve cardiac remodeling through counter-acting these events." (PMID 23861715, 2013). "MMP2-deficient mice showed reduced myocardial hypertrophy and fibrosis, while MMP9 deficiency partially improved myocardial hypertrophy and fibrosis following pressure overload." (PMID 22943504, 2012). "The investigators described cardiac hypertrophy, increase in the collagen deposition, c-jun, and matrix metalloproteinase 2 (MMP2) expressions in the heart." (PMID 20195525, 2010). "Interestingly, Cu repletion recovered MMP2 level and reduced cardiac fibrosis in a rat model of pressure overload-induced cardiac hypertrophy." (PMID 36818345, 2023). "In MMP-2 knockout mice cardiac hypertrophy under pressure overload was repressed." (PMID 33400052, 2021). "We examined the mechanism of estrogen depletion-induced collagen accumulation and fibrosis, which may occur through MMP-2 downregulation and cardiac hypertrophy." (PMID 29636852, 2018). "The present study, demonstrating that chymase inhibition significantly attenuated both cardiac hypertrophy and fibrosis, suggests that suppression of MMP-2 activation might contribute, at least in part, to the beneficial effects of chymase inhibition on cardiac remodeling." (PMID 40943161, 2025).
cardiac hypertrophy (continued). "Many studies have shown that MMPs, particularly MMP-2 and MMP-9, are involved in cardiac remodeling processes, such as cardiac hypertrophy and fibrosis." (PMID 40943161, 2025). "As the major role of Mmp2 is extracellular matrix (ECM) remodeling, reduced Meg3 levels help drive Mmp2 expression therefore reducing fibrosis and myocardial hypertrophy as well as improving diastolic function in a mouse model of TAC." (PMID 37796408, 2023). "In hypertensive SHR rats which developed cardiac hypertrophy, we also observed downregulation of MMP-9 mRNA while MMP-2 mRNA was preserved." (PMID 33400052, 2021). "Hypertensive patients with cardiac hypertrophy have been reported to have reduced plasma levels of MMP1, MMP2 and MMP9, while elevated plasma TIMP1 levels have been reported in hypertensive patients that correlated with diastolic dysfunction and LV fibrosis." (PMID 22943504, 2012). "Moreover, it has also been reported that targeted deletion of MMP-2 ameliorates myocardial remodeling in mice with chronic pressure overload, indicating that MMP-2 plays a critical role in the development of cardiac hypertrophy." (PMID 40943161, 2025). "Heart tissues of SHRs exhibited increased mRNA expression of ANP, BNP and β-MHC and protein expression of myocardial hypertrophy markers, including Collagen I, Collagen III, matrix metalloproteinase 2 (MMP 2) and matrix metalloproteinase 9 (MMP 9), compared with the age-matched WKY rats (p < 0.05)." (PMID 38715976, 2024). "In the present study, the protein expression of PARP16 was also increased in the heart tissue of Ang II-infused mice, accompanied with the upregulation of myocardial hypertrophy marker BNP, myocardial fibrotic markers (Collagen 1 and MMP2/9) and the inflammatory marker VCAM-1." (PMID 37219631, 2023). "In our meta-analysis, we demonstrate that collagens, matrix metalloproteinases MMP2 and MMP9, immune system markers and markers in the TGFß signaling, and cardiac hypertrophy pathway are upregulated in anthracycline-induced cardiomyopathy whereas the AKT pro-survival pathway is downregulated." (PMID 34052857, 2021). "Fenofibrate attenuates pressure overload-induced cardiac hypertrophy partly by inhibiting the binding of p65-NFκB to NFATc4, the c-Jun NH2-terminal kinase pathway, ERK activation, and MMP2 activity, as well as increasing high mobility group box 1 (HMGB1) levels in nuclei." (PMID 30105051, 2018). "In contrast to our observations of downregulation of MMPs, in animal models with induction of cardiac hypertrophy, MMPs are often found to be upregulated, i.e., under AngII infusion, induction of MMP-7 was shown; under norepinephrine infusion or pressure overload, MMP-2 was induced." (PMID 33400052, 2021).